CRP (C-reactive protein)
Diseases named in the same sentence as CRP in open-access papers (continued):
Sharing a sentence is not in itself a finding about the gene and the disease.
Lipedema (2 papers, 2025). Disorder of adipose tissue characterized by symmetric and bilateral enlargement of the lower extremities due to abnormal deposition of subcutaneous fat often in obese women. "There was also evidence that lipedema in advanced disease states was associated with increased amounts of systemic CRP." (PMID 40149538, 2025). "Following the intervention diet, reduction in CRP (−0.39, p = 0.016) and IL-6 levels (−0.33, p = 0.034) in lipedema were observed." (PMID 41010539, 2025). "Elevated levels of IL-6 and CRP in the blood indicate activation of the inflammatory response and are commonly observed in chronic diseases, as well as in lipedema." (PMID 41010539, 2025). "Recent studies found that ketogenic diet may lower levels of systemic inflammatory markers (TNF-α and CRP) in patients with lipedema." (PMID 41010539, 2025). "A significant positive association was observed between the intervention diet’s DII and CRP (r = 0.55, p = 0.005), and between the baseline diet’s DII and IL-6 (r = 0.50, p = 0.013) in lipedema group." (PMID 41010539, 2025). "Recent studies have reported elevated serum concentrations of inflammatory markers such as CRP (C-reactive protein) and TNF-α (tumor necrosis factor-alpha) in lipedema patients." (PMID 41010539, 2025). "Biomarkers for lipedema diagnosis are still lacking, and cytokine, CRP, and amino acid levels in the serum of patients and controls have been considered for this purpose." (PMID 40149538, 2025).
liposarcoma (2 papers, 2021 to 2025). A usually painless malignant tumor that arises from adipose tissue. "Increased median values of CRP, NLR, and PLR were significantly higher in patients with dedifferentiated liposarcoma (DDLPS) (p < 0.001)." (PMID 40025678, 2025).
lung abscess (2 papers, 2024 to 2025). A bacterial, fungal or parasitic abscess that develops in the lung parenchyma. "Therefore, we recommend that ill infants with a positive COVID‐19 PCR test and elevated CRP levels be evaluated for secondary bacterial infections, including lung abscesses." (PMID 40370484, 2025).
lymphedema (2 papers, 2018 to 2021). Excess fluid collection in tissues, causing swelling. "The mean difference (SD) CRP values were 32.5 (46.5) mg/L for patients with lymphedema and 39.1 (40.5) mg/L for patients without lymphedema (p = 0.831)." (PMID 33810068, 2021).
membranoproliferative glomerulonephritis (2 papers, 2012). Inflammation of the glomeruli characterized by deposits at the intraglomerular mesangium, resulting in thickening of the glomerular basement membrane, activation of complement, and impaired kidney function secondary to damaged glomeruli. "In HCV-associated MC, other constituents include C1q, C-reactive protein (CRP), HCV antigens, and molecules of the lectin complement pathway (MBL and MBL-associated serine protease-1), the latter associated with membranoproliferative glomerulonephritis." (PMID 22956968, 2012). "Other constituents include also C1q, C-reactive protein (CRP), other HCV antigens (Ags), and molecules of the lectin complement pathway (MBL and MBL-associated serine protease-1), with the latter mostly associated with membranoproliferative glomerulonephritis." (PMID 23202510, 2012).
Methicillin-resistant Staphylococcus aureus (2 papers, 2020 to 2025). "The poor general condition of patients, high preoperative C-reactive protein (CRP) level, repeated joint surgeries, and Methicillin-resistant Staphylococcus aureus (MRSA) infections may be associated with lower DAIR success rate." (PMID 35236454, 2020).
mineral and bone disorders (2 papers, 2016 to 2025). "These significant associations persisted after further adjustment for clinical factors related to malnutrition-inflammation-atherosclerosis (MIA) syndrome (serum albumin, CRP, and hemoglobin) (model 2) and mineral and bone disorders (MBD) (1,25-dihydroxyvitamin D3 and whole PTH) (model 3)." (PMID 27662624, 2016).
mitral valve disease (2 papers, 2022 to 2023). "Herein, we measured CRP levels in the VHD patients and detected elevated CRP levels in all three forms of VHD, including aortic, mitral, and combined aortic and mitral valve disease." (PMID 35535358, 2022).
Moyamoya disease (2 papers, 2023 to 2024). Moyamoya disease (MMD) is a rare intracranial arteriopathy involving progressive stenosis of the cerebral vasculature located at the base of the brain causing transient ischemic attacks or strokes. "In conclusion, our study has demonstrated that elevated CRP levels and high triglycerides are independently associated with the progression of Moyamoya disease." (PMID 38167529, 2024). "Additionally, the study examined the association between CRP levels, an inflammation marker, and the progression of moyamoya disease." (PMID 38167529, 2024). "Although no significant subgroups could be categorized, the observed increase in CRP levels suggested a potential association between inflammatory markers and the progression of moyamoya disease." (PMID 38167529, 2024). "The study examined the association between chemical markers, such as triglyceride and C-reactive protein (CRP), and the progression of moyamoya disease." (PMID 38167529, 2024). "Increased CRP levels and white blood cell (WBC) count were significantly associated with moyamoya disease progression." (PMID 38167529, 2024). "Elevated triglyceride, CRP, and inflammation markers, as well as decreased rCVR, are potential predictors of moyamoya disease progression and complication types." (PMID 38167529, 2024). "Overall, these findings provide insights into the potential role of chemical markers, such as triglyceride and CRP, in predicting the progression of moyamoya disease." (PMID 38167529, 2024). "Third, considering the rarity of moyamoya disease, this study lacks prospective randomized controlled studies and does not consider other parameters (such as erythrocyte sedimentation rate, cytokine, and C-reactive protein), and the number of inflammatory factors studied is small." (PMID 37153657, 2023).
multiple system atrophy (2 papers, 2018 to 2022). Multiple system atrophy (MSA) is a neurodegenerative disorder characterized by autonomic failure (cardiovascular and/or urinary), parkinsonism, cerebellar impairment and corticospinal signs with a median survival of 6-9 years. "Moreover, lower CSF levels of neurofilament light chain, t-tau, YKL-40, and C-reactive protein were found in PD patients compared to those with multiple system atrophy." (PMID 36446820, 2022). "Similar results were obtained using the Unified Multiple System Atrophy Rating Scale (UMSARS) total score (mean total score = 53.3, SD = 16.1) with CRP and IL-8 (p = 0.018, β = 0.618 and p = 0.039, β = 0.526 respectively)." (PMID 30185816, 2018).
muscle atrophy (2 papers, 2014 to 2023). The loss of muscle tissue due to inactivity or disease. "Muscle atrophy during CT is associated with an increase in inflammatory cytokines, such as CRP, and related higher energy expenditure." (PMID 37946297, 2023).
muscular atrophy (2 papers, 2019 to 2021). "CRP is a pro-inflammatory cytokine and has been proposed as a possible cause of muscular atrophy and also associated with sleep deprivation in high concentrations." (PMID 31817603, 2019). "Moreover, sleep deprived individuals show higher circulating levels of c-reactive protein (CRP), which is associated with muscular atrophy." (PMID 33714959, 2021).
myasthenia (2 papers, 2023 to 2024). "In different clusters, symptom duration, severe myasthenia, cardiac involvement, serum inflammatory marker levels (ESR, CRP, C4), and CD163+ macrophage distribution were confirmed as discriminators." (PMID 38651547, 2024).
myelitis (2 papers, 2025). An inflammatory process affecting the spinal cord. "Subsequently, the patient developed myelitis and ADEM, which were characterized by impaired consciousness, elevated C-reactive protein levels, raised intracranial pressure, elevated white blood cell and protein levels in the CSF, and abnormal signals in the intracranial region and spinal cord." (PMID 40766314, 2025).
nasal cavity disease (2 papers, 2024 to 2025). "In this prospective blinded study, canine C-reactive protein (c-CRP), haptoglobin (HPT), and 25-hydroxyvitamin-D (25(OH)D) were investigated for their diagnostic value in 55 dogs with nasal cavity disease (ND)." (PMID 39409857, 2024). "Canine CRP concentrations were not significantly increased in this group of dogs in contrast to dogs with nasal cavity diseases but from healthy dogs (Kruskal–Wallis test; p = 0.0045)." (PMID 39409857, 2024). "These conditions therefore do not make CRP a good marker for monitoring nasal cavity disease." (PMID 40260215, 2025).
Nephroblastoma (2 papers, 2018 to 2024). An embryonal neoplasm characterized by the presence of epithelial, mesenchymal, and blastema components. "Nevertheless, in the case of Wilms tumor, although studies have shown correlations between C-reactive protein (CRP), lymphocyte-to-monocyte ratio (LMR), and prognosis, there is still a lack of simple, systematic, real-world data analysis based on blood cells." (PMID 39543678, 2024).
neurosarcoidosis (2 papers, 2022 to 2023). A sarcoidosis that involves the nervous system. "Elevated levels of sIL-2R in serum (40.0 vs. 5.0%, p = 0.007) and CSF (38.1 vs. 0.0%, p = 0.002) as well as elevated serum CRP (25.9 vs. 0.0%, 0.014) showed a strong association with neurosarcoidosis compared to MS." (PMID 37034091, 2023). "Comparison of serum sIL-2R, CSF sIL-2R and serum CRP levels between patients with neurosarcoidosis and patients with MS." (PMID 37034091, 2023). "Our data show that additional parameters such as CRP in serum and lactate in CSF are also attractive candidates for inclusion in combined laboratory parameter sets to distinguish neurosarcoidosis from MS." (PMID 37034091, 2023). "Accordingly, serum sIL-2R levels, CSF sIL-2R levels and serum CRP levels were significantly higher in neurosarcoidosis than in MS patients." (PMID 37034091, 2023).
occupational asthma (2 papers, 2013 to 2017). Asthma attacks caused, triggered, or exacerbated by OCCUPATIONAL EXPOSURE. "Increased serum total protein was also shown in subjects with occupational asthma, which may be due to increased γ globulin, C reactive protein and other protein structured inflammatory mediators." (PMID 24175050, 2013).
Optic neuropathy (2 papers, 2015 to 2020). "During the first visit we performed a laboratory evaluation including complete blood count, erythrocyte sedimentation rate (ESR), and C-reactive protein (CRP), considering other potential causes of optic neuropathy, and we prescribed oral prednisone 25 mg per day." (PMID 26770856, 2015).
oral premalignant lesion (2 papers, 2018 to 2022). "Metgud R and Bajaj S (2016) reported that salivary and serum concentrations of CRP were higher in OSCC and oral premalignant lesion patients compared to healthy individuals, highlighting how the increase in the CRP levels was strictly related to disease progression." (PMID 36005828, 2022).
oropharyngeal cancer (2 papers, 2020 to 2023). Carcinoma, predominantly squamous cell, arising from the epithelial cells of the oropharynx. "In summary, this study supports a causal relationship between CRP levels and an increased risk of oral and oropharyngeal cancers." (PMID 38071306, 2023). "This study supports that CRP was causally associated with an increased risk of oral and oropharyngeal cancer." (PMID 38071306, 2023). "The pre-treatment CRP level seems to represent a prognostic factor for CSS, OS, and LC in patients with oral and oropharyngeal cancer, particularly in those treated with definitive (chemo-) radiotherapy." (PMID 32182693, 2020). "The purpose of the present study was to evaluate the prognostic significance of the pre- treatment C-reactive protein (CRP) level in a cohort of 503 patients with oral and oropharyngeal cancer treated at a tertiary academic center between 2000 and 2017." (PMID 32182693, 2020).
osteomalacia (2 papers, 2021). Disorder caused by an interruption of the mineralization of organic bone matrix leading to bone softening, bone pain, and weakness. "Serum phosphorus levels, erythrocyte sedimentation rate (ESR), C-reactive protein (CRP) levels, and bone mineral density (BMD) were significantly lower in the osteomalacia group than the SpA/AS group (P < 0.05)." (PMID 34095182, 2021). "Serum phosphorus levels, erythrocyte sedimentation rate (ESR), C-reactive protein (CRP) levels, human leukocyte antigen (HLA)–B27 positivity rate, and BMD of the lumbar vertebrae and femoral neck were significantly lower in osteomalacia than in patients with SpA/AS (P < 0.05)." (PMID 34095182, 2021).
ovarian dysfunction (2 papers, 2021 to 2023). The inability of the ovaries to function. "Abnormal levels of cytokines, such as TNF-ɑ, IL-6, IL-8, IL-10, IL-18, IL-33, and C-reactive protein (CRP), result in ovarian dysfunction." (PMID 37062827, 2023).
ovarian serous adenocarcinoma (2 papers, 2012 to 2019). An adenocarcinoma that arises from the ovary and is characterized by the presence of malignant epithelial cells that, in well differentiated tumors, resemble the epithelium of the fallopian tube or, in poorly differentiated tumors, show anaplastic features and marked nuclear atypia. "The differential expression of CA125 between serous and non-serous ovarian cancer histotypes suggests that additional biomarkers such as CRP, SAA, IL6 and IL8 may complement the diagnostic efficacy of CA125, particularly for non-serous histotypes." (PMID 22410202, 2012).
pancreatic diseases (2 papers, 2014 to 2021). "Although the CRP preoperative assessment is not a common practice, in our institution, it is included in protocols for research purposes for pancreatic diseases." (PMID 34064877, 2021).
paracoccidioidomycosis (2 papers, 2023 to 2025). A systemic fungal infection caused by Paracoccidioides brasiliensis that is most often seen in immunocompromised patients. "Analysis of iron parameters and CRP levels according to disease severity of patients with chronic paracoccidioidomycosis before treatment." (PMID 37347744, 2023).
Paralytic ileus (2 papers, 2009 to 2012). "In this report, our patient demonstrated, on admission, a toxic high plasma CLZ level accompanied by paralytic ileus and an elevated CRP." (PMID 22934219, 2012).
parasite (2 papers, 2021 to 2023). "Parasitic infections, which are frequently found in LMIC, did not influence CRP levels; hence there would be no need to rule out these infections to interpret the results of CRP." (PMID 34574070, 2021).
Parvovirus infection (2 papers, 2014 to 2025). "Parvovirus infection triggers an intense intestinal inflammatory response, stimulating hepatocytes to synthesize CRP and leading to marked serum CRP elevation." (PMID 40843250, 2025).
penile squamous cell carcinoma (2 papers, 2016). "The preoperative levels of C-reactive protein (CRP) and body mass index (BMI) were determined and used to predict survival in patients with penile squamous cell carcinoma using data from a few studies." (PMID 26980738, 2016). "In recent studies, the preoperative levels of C-reactive protein (CRP) were found to predict survival in patients with penile squamous cell carcinoma." (PMID 27386948, 2016).
Platelet disorders (2 papers, 2024). "Hereto, platelets were treated with P2Y12 inhibitor cangrelor or cyclo-oxygenase 1 inhibitor indomethacin to mimic platelet disorders, followed by stimulation with either CRP-XL or NbD2 tetramers." (PMID 39512585, 2024). "Platelet disorders and abnormal levels of ESR, CRP, serum troponin, serum ferritin, D-dimer, and albumin were risk factors for cardiovascular involvement, and consequently, echocardiography is recommended in MIS-C patients with these laboratory indications." (PMID 39570835, 2024).
pneumococcal bacteremia (2 papers, 2018 to 2025). "A polymorphisms in the CRP promoter region is associated with the increased mortality in pneumococcal bacteremia patients." (PMID 41214213, 2025). "In the multivariate analysis, age < 65 years, serum albumin level < 3.0 g/dL, need for intensive respiratory or vasopressor support (IRVS), and C-reactive protein level > 20 mg/dL were identified as independent risk factors for the development of pneumococcal bacteremia." (PMID 29382316, 2018). "Human CRP has been shown to activate the mouse complement system, which is attributed to human CRP-mediated protection in mouse models of pneumococcal bacteremia." (PMID 41214213, 2025).
pneumococcal meningitis (2 papers, 2023 to 2024). An acute purulent infection of the meninges and subarachnoid space caused by Streptococcus pneumoniae, most prevalent in children and adults over the age of 60. "Remarkably, the CRP of the patient with pneumococcal meningitis increased from 20 mg/L at the time of hospital admission to a maximum value of 206 mg/L during the further follow-up in the hospital." (PMID 38539395, 2024).
poisoning (2 papers, 2021). A condition or physical state produced by the ingestion, injection, inhalation of or exposure to a deleterious agent. "Plasma CRP level may be useful for the prediction of prognosis in paraquat poisoning, and the difference in C-reactive protein value between initial and follow-up after 24 hours was associated with mortality in a study which included 96 subjects with acute organophosphate poisoning." (PMID 34457088, 2021). "The GCS score at presentation, creatinine level, and CRP level were analyzed by multiple logistic regression to identify predictors of ABI in cases of acute CO poisoning." (PMID 34071902, 2021).
post-pericardiotomy syndrome (2 papers, 2024 to 2025). "In summary, blood type O, valve-sparing root replacement and peak C-reactive protein >15 mg/dl within 48 hours postoperatively are significantly associated with post-pericardiotomy syndrome after native valve-sparing aortic valve surgery." (PMID 38941316, 2024). "PICS, post-cardiac injury syndrome; PPS, post-pericardiotomy syndrome; CIED, cardiac implantable electronic device placement; NSAIDs, nonsteroidal anti-inflammatory drugs; PCI, percutaneous coronary intervention; CRP, C-reactive protein." (PMID 39974595, 2025).
postpartum hemorrhage (2 papers, 2023 to 2024). Hemorrhage defined as a blood loss in excess of 500 mL after vaginal delivery or more than 1000 mL after a cesarean delivery. "Severe postpartum hemorrhage correlated with CRP, IL-13, and proteins of the IL-17 family." (PMID 39696496, 2024).
primary hyperparathyroidism (2 papers, 2022 to 2025). "In a cross-sectional analysis of 136 patients from the Eplerenone in Primary Hyperparathyroidism (EPATH) trial, investigators evaluated the association between inflammatory biomarkers—including CRP, KYN, quinolinic acid (QUIN), and TRP—and echocardiographic indicators of adverse cardiac remodeling." (PMID 40426950, 2025). "Dog four was subsequently diagnosed with primary hyperparathyroidism at the same visit, which may have influenced subsequent CRP concentrations." (PMID 35739930, 2022).
progressive supranuclear palsy (2 papers, 2020 to 2025). A rare late-onset neurodegenerative disease characterized by supranuclear gaze palsy, postural instability, progressive rigidity, and mild dementia. "Starhof and colleagues examined a panel of C-reactive protein (CRP) and cytokines among patients with PD, MSA, progressive supranuclear palsy (PSP) and health controls." (PMID 40336104, 2025).
psychosomatic disorders (2 papers, 2020 to 2022). "E2 was the only independent predictor of the psychosomatic disorders after adjusting for E4, CRP, gender, age and BMI." (PMID 32646381, 2020). "In a previous study, we demonstrated an association between the presence of the allele ε2 and improvement in all psychosomatic disorders, and positive and negative associations between c-reactive protein (CRP) and the alleles ε2 and ε4, respectively." (PMID 35205269, 2022).